RNVU1-25 (RNA, variant U1 small nuclear 25)
Synonyms: LOC124904634
Gene: Small nuclear RNA gene on chromosome 1 (146,409,903 to 146,410,062, forward strand). Ensembl gene ENSG00000274428.
Gene Ontology:
Molecular function: pre-mRNA 5'-splice site binding
Biological process: mRNA 5'-splice site recognition
Cellular component: U1 snRNP
Homologues: Orthologues: chimpanzee U1 (83% identical), chimpanzee U1 (82% identical), rabbit U1 (58% identical), zebrafish U1 (43% identical). Paralogues in human: RNVU1-26 (99% identical), RNVU1-24 (98% identical), U1 (98% identical), RNU1-1 (72% identical), RNU1-2 (72% identical), RNU1-27P (72% identical), RNU1-28P (72% identical), RNU1-3 (72% identical), RNU1-4 (72% identical), RNVU1-1 (72% identical), RNVU1-18 (72% identical), RNVU1-29 (72% identical), and 134 more.